AFP (alpha fetoprotein)
Diseases named in the same sentence as AFP in open-access papers (continued):
Sharing a sentence is not in itself a finding about the gene and the disease.
tumor (continued). "None of the mice developed measurable AFP or GLuc levels, and 7 weeks post injection there was no tumor visible at laparotomy." (PMID 21853130, 2011). "The pathological characteristics of serum HIF-1α were associated with the levels of circulating VEGF and Ang-2, the size of the tumor, and extrahepatic metastasis, and but not with patients’ gender, age, and AFP level." (PMID 22224081, 2011). "On univariate and multivariate analyses, better survival was significantly associated with a better Karnofsky performance status (KPS) and well-controlled intrahepatic tumor, but not with lower alpha-fetoprotein levels." (PMID 22107882, 2011). "Upon univariate survival analysis (Cox model), the following variables significantly impacted survival in the study group: nodule size 3,5 cm, multi-nodular HCC, gross vascular invasion, grading, AFP mRNA positivity, VEGF23 pg ml−1, Child-Pugh B–C, bi-lobar tumour, surgery, PST, TNM, and BCLC." (PMID 21912636, 2011). "The combination of AFP and CEUS provides a powerful tool to assess therapeutic effects on intrahepatic tumors, and well-designed animal studies should also include tumor histology to cross-validate CEUS data with histology, something that is hard to achieve in the clinical setup." (PMID 24281167, 2010). "In general, tumor biology and degree of invasiveness, as expressed by preoperative AFP values and microvascular invasion, rather than dimensional parameters showed a relevant impact on HCC recurrence." (PMID 20862199, 2010). "Anti-AFP Tc1 responses were detected in 28.5% of controls, as well as in 25% of HCC patients with Okuda I (early tumour stage) and in 31.6% of HCC patients with stage II or III (late tumour stages)." (PMID 20087354, 2010). "While AFP has been shown to correlate nicely with tumor size, it does not provide the location of tumor cells, thus in models of HCC tumor metastasis, tools such as IVIS are extremely valuable in locating the tumor." (PMID 24281167, 2010). "As limited objective tumour response is commonly observed in most targeted agent trials, we also assessed the therapeutic efficacy of ADI-PEG 20 by monitoring changes of the serum AFP levels." (PMID 20808309, 2010). "On immunohistochemistry tumor cells appeared positive for β-human chorionic gonadotrophin (β-hCG) and cytokeratins (AE-1, AE-2) and negative for octamer binding transcription factor (OCT)-3/4, α-fetoprotein (AFP) and CD-30." (PMID 21108779, 2010). "BLI provides an additional tool for monitoring orthotopic tumor models where the tumor is not visible and thus the estimate of tumor size is dependent on the use of a serum biomarker such as AFP." (PMID 24281167, 2010). "Tumor markers such as PSA, CA125, CA 19-9, and AFP were all within normal ranges." (PMID 19946546, 2009). "The tumor markers CEA and AFP were within the normal ranges." (PMID 19239719, 2009). "Tumour markers including alpha-fetoprotein (AFP), carcinoembryonic antigen (CEA) and Ca19-9 were within normal limits." (PMID 19538751, 2009). "At that time, although HCV-RNA was still negative, mild liver dysfunction was noticed along with a marked increase of tumor markers of HCC, namely alpha-fetoprotein (AFP) and des-gamma-carboxy prothrombin (DCP: PIVKA-II); being 164.9 ng/ml and 3692 mAU/ml, respectively." (PMID 19128460, 2009). "Tumor markers (PSA, CA125, CA 19-9 and AFP) were within normal ranges." (PMID 19946546, 2009). "None of these tumor types is characterized by elevated alpha-fetoprotein or imaging characteristics observed in our patient." (PMID 18928548, 2008). "Although overall AFP is elevated only in a minority of NET patient, this data analysis demonstrates the ability of AFP to highlight a group of NET patients with aggressive, high-grade tumours and poor prognosis." (PMID 18577995, 2008). "Moreover, the expressions of MAGE-A4 and SCP-1 were related to AFP abnormality, and the expression of NY-ESO-1 was related to early tumor stage." (PMID 17244360, 2007).
tumor (continued). "AFP and DCP are, however, the most useful serum tumor markers for detection of HCC, and the simultaneous determination of these markers might improve the accuracy, especially in differentiating HCC from precancerous lesions, and nonmalignant hepatopathy." (PMID 17244360, 2007). "As could be seen in, in some cases with H19 increased expression, the H19 message is abundantly expressed in a human HCC tumor, at a much higher level than the traditional HCC marker α-fetoprotein (AFP)." (PMID 17786216, 2007). "As can be seen, AFP is also expressed in the intravascular invasion of HCC, possibly teaching that H19 could serve as a tumor marker." (PMID 17786216, 2007). "High tumor marker levels were found: lactate dehydrogenase (LDH) of 1023 mU/ml; human chorionic gonadotropin β-subunit (βhCG) of 45050 mU/ml; and alpha-fetoprotein (AFP) of 3077 ng/ml (pT3N3M1BS2, AJCC stage IIIC)." (PMID 17322957, 2006). "Nevertheless, a presalvage chemotherapy biopsy may prove invaluable even in patients with elevated serum tumour markers, since HCG or AFP elevation may occur unrelated to MGCT." (PMID 16508636, 2006). "It uses the risk factors primary site, presence of nonpulmonary visceral metastases and tumour markers alpha-fetoprotein (AFP), human chorionic gonadotrophin (HCG) and lactic dehydrogenase (LDH)." (PMID 15026798, 2004). "Although PIVKAII is a tumour marker complementary to AFP for diagnosis of HCC, it has not been used in China." (PMID 12799630, 2003). "In patients with HCC, however, around one-third of small tumour (<3 cm) was shown to secrete little or no AFP into the circulatory system." (PMID 12454776, 2002). "Human chorionic gonadotrophin (hCG) and alphafetoprotein (AFP) were measured in culture media from a panel of 29 cell lines including 9 bladder carcinomas, 5 'normal' bladder epithelia, 10 germ cell tumours, and 5 miscellaneous tumours and 'normal' cell lines." (PMID 2441730, 1987). "Unlike albumin secretion, however, exposure of hepatic tumour cells to 2% DMSO did not further increase (but slightly decreased) extracellular AFP accumulation." (PMID 6194807, 1983). "MSP does not react with antisera raised to alpha 1 foetoprotein (AFP) or carcinoembryonic antigen (CEA) and hence is immunologically distinct from these other tumour-associated glycoproteins." (PMID 6158965, 1980). "Additionally, the proportions of patients with preoperative serum alpha-fetoprotein (AFP) >100 ng/mL, tumors adjacent to major intrahepatic vessels, and a maximum tumor diameter >3 cm were significantly lower in the complete ablation group compared to the incomplete ablation group (P<0.05)." (PMID 42306801, 2026). "The reasons for this could include a perceived aggressive biology of the tumor leading to physician bias in favor of TARE intervention or TARE enrollment in non-transplant centers, which are more prone to managing patients with HCC having higher AFP levels." (PMID 40647551, 2025). "Also, in this case, serum AFP levels were more parallel to tumor burdens than CA19-9, and we speculate that serum AFP plays a significant role in efficacy monitoring of PACC if positive." (PMID 41409298, 2025). "While there has been some success in this regard when considering changes in AFP during the first weeks of treatment (either alone or in combination with ALBI49), such an approach is not a true response prediction but rather a response assessment using the serum tumor marker AFP." (PMID 40059970, 2025). "Comparative analysis of tumor markers and hematological parameters before and after neoadjuvant therapy demonstrated significant reductions in serum CEA and CA19-9 levels in both the NACI and NAC groups (P < 0.05), while AFP levels didn’t change significantly (P > 0.05)." (PMID 40977738, 2025). "There was neither detection of tumor marker alpha-fetoprotein (AFP), CA19–9, nor CEA." (PMID 40426891, 2025). "Fifth, tumor characteristics and AFP level data was not calculated in this project." (PMID 39863701, 2025).
tumor (continued). "Additionally, AFP upregulates stem cell markers (CD44, CD133, EpCAM) and reprogramming proteins, supporting the expansion and maintenance of cancer stem-like cells, which are crucial for tumor initiation and progression." (PMID 41373846, 2025). "In addition, EIF5A2 expression was associated with tumor size, tumor grade, and TNM stage in LIHC (P < 0.05), but not with sex, age, AFP level, and vascular invasion." (PMID 40964657, 2025). "AFP and tumor size failed to prove as useful tools in predicting OS." (PMID 40075616, 2025). "However, the relationship between the amount of AFP secreted by HCC cells per unit volume and the degree of tumor malignancy and patient prognosis remains unclear." (PMID 40857604, 2025). "The IP-10 levels only showed a very weak correlation with Albumin-bilirubin (ALBI) score, Child-Pugh score, Branched-chain amino acids (BCAA), Branched-chain amino acids/tyrosine ratio (BTR), platelet counts, alpha-fetoprotein (AFP), and tumor size, with no alternative indicators." (PMID 40373032, 2025). "However, it remains unclear whether CTCs offer superior assessment of disease status compared to AFP and DCP, which are tumor markers commonly monitored in clinical practice." (PMID 40940925, 2025). "During tumor progression, these cells may undergo reverse/aberrant differentiation towards pluripotent embryonic stem cell-like states, leading to various pathological subtypes, including HAS, and concurrently acquiring the ability to secrete AFP." (PMID 41561743, 2025). "Notably, AFP and AFU are important tumor markers in the development of HCC." (PMID 40551431, 2025). "However, as AFP is not a specific marker for this tumor, the absence of AFP overexpression does not exclude a diagnosis of HAC." (PMID 40900781, 2025). "Additionally, the investigation into other inflammation scores (like PLR, NLR, and SII) and conventional serological tumor biomarkers (including CEA, CA72‐4, CA125, CA19‐9, and AFP) revealed limited effectiveness in distinguishing responders from non‐responders to combination immunotherapy." (PMID 41187909, 2025). "Tumour epithelial cells were further reclustered into two distinct subclusters (Subcluster 1 and Subcluster 2), and DUSP9 was predominantly expressed in Subcluster 1, which was enriched with other oncofetal and stemness‐related genes such as AFP, GPC3, IGF2, ANPEP and EPCAM." (PMID 41383134, 2025). "In this model, neither anti-PD-1 nor anti-PD-L1 monotherapy has shown significant efficacy; however, AFP immunotherapy combined with anti-PD-L1 can significantly inhibit the progression of HCC, while the combination with anti-PD-1 can induce a slowdown in tumor progression." (PMID 41514551, 2025). "In addition, immunohistochemical staining showed that tumor cells exhibited negative staining for alpha-fetoprotein (AFP), anti-endomysial antibody (EMA), and hepatocyte paraffin 1 (HepPar-1)." (PMID 40538841, 2025). "In addition to these image findings, elevated serum α-fetoprotein (AFP) and lectin-reactive fraction of AFP levels made us resect the liver mass without performing a biopsy to the tumor under the tentative diagnosis of possible hepatic malignancy." (PMID 40248561, 2025). "The patients that benefitted the most according to the subgroup analysis were patients > 60 years old; those with lower levels of AFP (≤400 ng/mL); more than three tumors, with the largest tumor size < 4 cm; and those without hepatitis B infection and liver cirrhosis." (PMID 40361498, 2025). "Tumor markers like alpha-fetoprotein and cancer antigen 19-9 were not checked." (PMID 40994806, 2025). "Unlike conventional imaging or serum tumor markers (e.g., AFP, CEA), ctDNA assays offer greater sensitivity and specificity, which may eventually render some traditional diagnostics obsolete." (PMID 40563578, 2025).
tumor (continued). "In asymptomatic (painless) girls, the surgeon has enough time to perform reliable imaging (ensuring that the tumour does not show any sign of malignancy) and to dose tumour markers alpha-fetoprotein, human chorionic gonadotrophin, Inhibin B, anti-Mullerian hormone and Calcemia." (PMID 41585072, 2025). "Interestingly, in our study, decreased AFP levels following second‐line treatment were not correlated with patient prognosis or tumor response." (PMID 40047078, 2025). "Often, crucial clinical information, such as serum levels of tumor markers (CA19-9, AFP), lesion size and location, history of previous neoplasms, and clinical hypotheses, is not properly shared, compromising the diagnosis and, therefore, the therapeutic approach." (PMID 39813555, 2025). "While AFP is a direct marker of tumor biology and remains superior to other inflammation-based biomarkers, it is known that elevated AFP levels may not be present during HCC diagnosis." (PMID 40181742, 2025). "Assessment of HAC markers revealed that the tumor cells were positive for AFP and glypican-3; negative for Sal-like protein 4; strongly positive for human epidermal growth factor receptor 2 (3+); positive for Brahma-related gene 1 and retinoblastoma 1; and negative for CD117 and S100." (PMID 40900781, 2025). "Attempts to further refine the model by adding additional tumour markers, such as alpha-fetoprotein (AFP) and CA125, did not significantly improve its predictive capability, as seen in the negligible increase in R2 values and non-significant p-values (p = 0.480 and p = 0.479, respectively)." (PMID 40332145, 2025). "When dividing by post-treatment PIVKA-II levels (>40 mAU/mL), the high-tumor-marker group exhibited a non-significant decrease in AFP levels from 10.4 ng/mL to 2.4 ng/mL (p = 0.084), whereas PIVKA-II levels significantly decreased from 42.0 mAU/mL to 27.0 mAU/mL (p = 0.019)." (PMID 40002160, 2025). "As one of the pro-angiogenic factors, AFP can promote the abnormal proliferation of blood vessels by binding to vascular endothelial growth factor receptor 2 (VEGFR2), increase the permeability and structural instability of tumor blood vessels, and accelerate the process of hematogenous metastasis." (PMID 41200181, 2025). "In biology, high AFP level is closely related to the activation of Fibroblast growth factor receptor (FGFR) pathway, and TKI drugs can effectively block FGFR and VEGFR signaling pathways, thereby inhibiting tumor angiogenesis, improving tumor perfusion, and enhancing follow-up treatment response." (PMID 41200181, 2025). "It will be crucial to evaluate whether the iRGD-induced tumour-blood transport occurs in patients with HCC and other tumours as revealed by changes in the blood levels of tumour-derived markers such as the clinical tumour markers AFP and PSA or emerging tumour markers." (PMID 38889481, 2024). "Thus, a concurrent focus on both AFP and DCP may provide more comprehensive information on tumor biology and prognosis than a singular focus on either marker." (PMID 38903723, 2024). "The iRGD-induced increase in the blood AFP concentration in HCC mice could be due to the stimulation of AFP secretion from the tumour cells rather than an iRGD-induced tumour-to-blood transport of AFP." (PMID 38889481, 2024). "In conclusion, upregulation of SNHGs expression correlates with shorter OS, RFS, DFS, tumor size and numbers, histologic grade, lymphatic metastasis, vein invasion, tumor stage, PVTT, and AFP level, suggesting that SNHGs may serve as prognostic biomarkers in HCC." (PMID 38634194, 2024). "However, serum AFP is generally high in patients with HAS, but other tumor markers remain normal." (PMID 39186327, 2024). "AFP is the most widely used serum biomarker in HCC and may reflect tumor burden and aggressiveness." (PMID 38681863, 2024).
tumor (continued). "Moreover, fluorescent IHC (F-IHC) analyses revealed a diminished intensity of staining for the stemness-related marker OCT4, alongside an intensified staining for markers indicative of differentiation (AFP, ACTA2 and CD57) in xenograft tumor tissues following SERPINB9 knockdown." (PMID 39528470, 2024). "However, initial tumor size, AFP level, and SEER stage did not yield any statistically significant association with PIL presence." (PMID 38658868, 2024). "Additionally, there was a negative correlation between the AFP level (rs = −0.23, p = 0.32), tumor grade (rs = −0.46, p = 0.06) and the number of CTCs in the HCC group." (PMID 39791707, 2024). "Furthermore, it has been noted that some AFP-negative patients still exhibit aggressive tumor behavior, challenging the reliance on AFP as a sole prognostic indicator." (PMID 39839797, 2024). "Similarly, more patients in the non-screened cohort had a baseline AFP ≥400 ng/mL, potentially reflecting an increased tumor burden when HCC is diagnosed outside of a screening protocol compared to diagnoses made within the context of screening protocols." (PMID 39594783, 2024). "Tumor markers such as alpha-fetoprotein (AFP) and carcinoembryonic antigen (CEA) were negative." (PMID 38745658, 2024). "However, CA199, CA15-3, AFP, and HE4 tumor markers were within normal limits." (PMID 38968462, 2024). "The prognostic relevance of AFP and DCP may be attributed to the hypothesis that their expression levels are not only related to tumor morphological parameters but also to the biological behavior of the tumor, both of which are important factors for patient prognosis." (PMID 38903723, 2024). "AFP was low in 25/31 and high in 6/31; through imaging (both abdominal ultrasound and MRI) these nodules were consistent with macroregenerative/benign hepatocellular hyperplastic nodules in 17 patients, FNH in 2, dysplastic nodule in 2, and suspicious for a tumor in 10 (6 with a high level of AFP)." (PMID 38254797, 2024). "In our study, the two patients with elevated AFP levels were 4 months and 8 months old, suggesting that their elevated AFP levels could be related to their age rather than the malignancy of the tumor." (PMID 39606696, 2024). "In addition, HCC tissues of patients with higher alpha fetoprotein (AFP) level (>20 μg/L), incomplete tumor encapsulation, poorer differentiation grade (III and IV), earlier recurrence (<2 years), multiple tumor numbers, and satellite nodules showed lower CREB3 staining intensity." (PMID 38952575, 2024). "AFP CAR-T cells effectively kill tumor cells without inducing cytokine release syndrome." (PMID 39136031, 2024). "Similarly, in our study, a trend toward higher AFP levels was observed in the low LMR group, further fueling speculation about the LMR’s potential to reflect the balance between the tumor and the host immune surveillance." (PMID 39057108, 2024). "Besides clinicopathological variables such as macrovascular invasion, tumor number, tumor size, TNM stage, and alpha-fetoprotein level, IL-8 and integrin β3 expression were proved to be able to predict prognosis based on univariate analysis (P < .05, respectively)." (PMID 39465852, 2024). "The maximum tumor diameter was moderately correlated with DCP levels rather than AFP." (PMID 36672339, 2023). "Further, in those patients whose information regarding tumor markers could be obtained, the AFP levels were all negative." (PMID 37251926, 2023). "In patients with pretransplant LRT, a single AFP level could not be used for evaluating tumor aggressiveness." (PMID 36900345, 2023). "The AFP level produced by a neoplasm may not exceed the physiological concentrations observed in infancy." (PMID 37686577, 2023). "In addition, although a higher tumor burden was accepted, we did not observe increased rates of tumor characteristics related to worse prognosis, such as microvascular invasion, probably owing to additional restrictions regarding alpha-fetoprotein." (PMID 38138897, 2023).